HDAC1 (histone deacetylase 1)
Diseases named in the same sentence as HDAC1 in open-access papers (continued):
Sharing a sentence is not in itself a finding about the gene and the disease.
cancer (continued). "As an epigenetic factor, RBBP7 binds to histone deacetylase 1 (HDAC1) and specificity protein 1 (Sp1) to exert complicated and contradictory functions in cancer development." (PMID 35538026, 2022). "The RT-qPCR method revealed that EGCG triggered anti- cancer epigenetic alterations, including downregulation of epigenetic regulators DNMT1, HDAC1, HDAC2, and G9a." (PMID 35327559, 2022). "Both HDACs and LSD1 are highly expressed in various cancer types, and LSD1 is itself a substrate for HDAC1-mediated deacetylation at Lys374, which influences histone binding." (PMID 36497494, 2022). "HDAC1, HDAC2, and LSD1 are found together in transcriptional repressor complexes, such as NuRD, CoREST, and Sin 3A, which promote cancer cell survival." (PMID 36497494, 2022). "Compound 12a exhibited good inhibitory activities against ALKwt or HDAC1 enzymes and synergistically inhibited proliferation of ALK-driven cancer cells via inducing cell apoptosis and cell cycle arrest." (PMID 36100230, 2022). "The class I HDACi entinostat (MS-275) is a synthetic benzamide derivative with preference for HDAC1 and HDAC3 enzymes undergoing clinical trials for several types of cancer." (PMID 35994477, 2022). "Class I histone deacetylases, HDAC1, HDAC2, and HDAC3, represent potential targets for cancer treatment." (PMID 35458724, 2022). "Malignant cell clusters shared cancer characteristics and widely significantly overexpressed HLA-A, HLA-B, MCL1, HDAC1, LCK, HSPB1, and IL6R, indicating a common tumor origin." (PMID 36131282, 2022). "Mechanistically, we showed that miR‐34c regulates Notch signaling and other cancer related pathways by targeting multiple genes (CCNE2, E2F2, E2F5, and HDAC1)." (PMID 35509638, 2022). "According to reports, histone deacetylase 1 (HDAC1) is a member of HDAC family and an important epigenetic factor, which is related to the progress and prognosis of cancer." (PMID 35756488, 2022). "HDAC1 was shown to be one of the oncogenes deleted in the 1p deletion event, and SIRT2 and EP300 were two cancer suppressors lost in 19q deletion and 22q deletion events, respectively." (PMID 33718432, 2021). "Since RS and DNA damage also occur endogenously in rapidly growing cancer cells, such cells should be selected for low CBP/p300 and high HDAC1,‐2,‐3 expression." (PMID 34258881, 2021). "Tissue expression was confirmed to be significantly different in cancer vs. control samples for DNA2, MAOA, PARP1, TYR, and HDAC1 in the IST Online database and for PTK2B, MAOA, PARP1, and TYR in the GEPIA2 database." (PMID 34199192, 2021). "Repression of HDAC1 and HDAC7 by miR-34a reduced deacetylation of HSP70 K246, which promotes cancer cell survival and therapy resistance by inhibiting autophagy." (PMID 33763422, 2021). "Similar to HDAC1 in structure, HDAC2 has been shown vital in cardiac hypertrophy, Alzheimer’s disease, Parkinson’s and cancer." (PMID 34880761, 2021). "Moreover, the SphK1/SphK2 product, S1P was shown to target histone deacetylases (HDAC1/2), tumor necrosis factor receptor associated factor 2 (TRAF2), human telomerase reverse transcriptase (hTERT), and NF-κB nuclear activities linked to cancer initiation and progression." (PMID 33919234, 2021). "The GDSC data set had a total of 47 unique drugs with ten targets, including EGFR, IGF1R, HDAC1, PARP2, AURKA, and BRAF, as well as their sensitivities across 224 cancer cell lines." (PMID 33795761, 2021). "The CTD2 data set had a total of 79 unique drugs with sensitivities across 351 cancer cell lines that involve 22 targets, such as EGFR, HDAC1, MTOR, MET, ERBB2, and BRAF." (PMID 33795761, 2021). "Thymoquinone also downregulates the expressions of containing plant homeodomain (PHD) and really interesting new gene (RING) finger domains 1 DNMT1,3A,3B, (UHRF1), HDAC1,4,9, G9A, KMT2A,B,C,D,E, and KDM1B genes in Jurkat cells and MDA‐MB‐468 cancer cell lines." (PMID 33747489, 2021).
cancer (continued). "Expression analysis of treated tumors identified decreased expression of pediatric cancer markers and EZH2 targets, only after combined treatment, supported by Co-IP experiments confirming an interaction of PRC2 together with HDAC1 and 2 in EwS cells." (PMID 34654445, 2021). "We explored here the expression profile of HDAC family via Oncomine database, which indicated that HDAC1, HDAC2, HDAC3, HDAC7, HDAC8, and HDAC9 expressed highly in pan‐cancer at transcriptional level." (PMID 34308568, 2021). "We also performed real-time PCR (RT-PCR) with cDNAs from human STS samples and analyzed the clinical significance of class I HDAC expression including HDAC1, HDAC2 and HDAC3, in 49 patients with different subtypes of STS treated at our cancer center." (PMID 33637599, 2021). "All anti-cancer activities are given by activation or inhibition of pathways such as HDAC1/PTEN/Akt, EGFR/ErbB2/ErbB3, and PI3K/Akt; PI3K-AK-mTOR, HDAC1/PTEN/Akt; Wnt/β-catenin." (PMID 32923398, 2020). "In vitro inhibition of HDAC1 and 6 by the hybrid inhibitors with different combinations of linkers and cap groups and antiproliferative activity (MTT assay) against the human cancer cell lines Cal27, U87 and U251." (PMID 32780485, 2020). "HDAC1 and BRD2 were highly expressed in PDA compared to normal pancreas, both in humans and in epithelial and mesenchymal cancer cells in KIC mice." (PMID 33244070, 2020). "Histone deacetylase 1 (HDAC1) transcription is induced by NANOG, which is key to these NANOG-dependent phenotypes of cancer cells." (PMID 32455616, 2020). "All the compounds, 55a–p, inhibited histone deacetylase 1 (HDAC1), a key HDAC subtype shown in cancer cell differentiation and proliferation." (PMID 32784935, 2020). "In mice, the relative expression of HDAC and BET proteins is similar, except for the reciprocal pattern of HDAC1 and HDAC11 in ADM and primary PDA cancers." (PMID 33244070, 2020). "In the cancer model, entinostat neutralizes MDSC and Tregs 18 and HDAC1 conditional KO T cells increases IFN-γ production." (PMID 32368288, 2020). "Further, this analysis also strongly suggested that SNAI2, SUZ12 and HDAC1 might form a repressor complex, implicating the interaction of transcriptional factors and histone modification regulators to have a pivotal role in miR-204-5p-mediated inhibition of cancer progression." (PMID 31938073, 2020). "HDAC1, 2, 3, 4, and 7 were reported to be upregulated in PDA, whereas HDAC 2 and 3, along with SIRT1, have been reported to be involved in cancer invasion and chemo-resistance." (PMID 33244070, 2020). "Again, genes such as GADD45B (growth arrest and DNA-damage-inducible, beta), HDAC1 (histone deacetylase 1), and MCM3 (minichromosome maintenance complex component 3) were oppositely coordinated in the cancer nodule in contrast to the normal tissue." (PMID 33302383, 2020). "Since EGFR expression is regulated by multiple factors, including specific protein (Sp) transcioption factors through interaction with HDAC1 and HDCA2 in cancer cells 19, 20, we tested the effect of Sp1 and Sp3 knockdown on EGFR activity and HDCA expressions." (PMID 32226300, 2020). "Single knockdown of HDAC1, HDAC2, HDAC3, LSD1, DNMT1, and EZH2 generated different effects of neuron-like differentiation in cell lines of different cancer types." (PMID 31130994, 2019). "Specifically, levels of the pVHL and RhoA were decreased, and the expression of HDAC1, CD44 (a cancer stem cell [CSC] marker), Snail, and vimentin (EMT markers) in normal hRECs and various renal tumor cell types (Caki-2, ACHN, and 798-o) was upregulated." (PMID 30872677, 2019). "Taken together these data indicate that HDAC1, binding to the RUNX2 P2 promoter, prompts RUNX2 expression in cancer cells." (PMID 31395086, 2019). "The Cancer Genome Atlas (TCGA) dataset analysis revealed that HDAC4, HDAC7 and HDAC9 as well as HDAC class I members HDAC1 and HDAC2 is significantly correlated with patient survival." (PMID 31635225, 2019).
cancer (continued). "Due to stronger effect of EZH2 knockdown on neuronal differentiation in different cancer cells, we subsequently focused on the role of EZH2 in the regulation of expression of HDAC1, LSD1, or DNMT1, and of β-CAT and SMAD transducers as well." (PMID 31130994, 2019). "Here, we show that EZH2, LSD1, DNMT1, and HDAC1 form interactions themselves, meanwhile, they also interact with SMAD proteins and β-CATENIN in cancer cells." (PMID 31130994, 2019). "One of these, the class I HDAC inhibitor entinostat (HDAC1>HDAC3), was previously shown to restore SLFN11 expression and sensitivity to DNA damage in resistant cancer cell lines." (PMID 31632920, 2019). "Analysis of RNA-seq data from 34 normal gastric tissues and 415 primary GC revealed significant upregulation of B7-H1; HDAC1–3, 6–8, and 10; and SIRT1, 3, 5, and 6 and downregulation of HDAC5 and SIRT4 in cancer (only data of B7-H1 and HDAC1–3 was presented)." (PMID 30537988, 2018). "In the current study, we investigated romidepsin, an HDAC1 and HDAC2 inhibitor, that has been used as an anticancer drug and is known to induce cancer cell cycle arrest, cancer cell differentiation, and cell death." (PMID 29731773, 2018). "Since HDAC (HDAC1, HDAC2) expression and activity are frequently increased in cancers and that epigenetics has been shown to be crucial in cancer biology, the project to use HDACis to fight cancer progression emerged more than 15 years ago." (PMID 29754883, 2018). "Western blot results showed that HDAC1, HDAC2, and HDAC3 expression change between cancer, and adjacent tissue was consistent with the B7-H1 level change in 8 (66.7%), 9 (75.0%), and 9 (75.0%) cases, respectively." (PMID 30537988, 2018). "Cancer cell lines (CAL-27 and SACC-83) were exposed to pan-HDAC inhibitor, or HDAC1 inhibitor, or geranylgeranyl transferase type I (GGTase-I) inhibitor alone or in combination with statin." (PMID 28481295, 2017). "Depending on the cellular context, HDAC1 and HDAC2 can either exist in predominantly heterodimer form in both normal and cancer cells, function independently, or potentially act as homodimers in other cellular contexts such as in mouse fibroblasts." (PMID 28982113, 2017). "Currently, HDAC inhibitors are used in the clinical setting as anti-cancer (vorinostat, an inhibitor of HDAC1, 2, 3, and 6) or psychotropic (VPA, an inhibitor of HDAC1, 2, 3, and 8) drugs." (PMID 28886131, 2017). "HDAC1 belongs to HDAC class I and is elevated in a variety of cancers, such as gastric, colorectal, lung cancer, bladder cancer." (PMID 28624794, 2017). "To delineate which HDAC family member(s) play an important role in repressing FBP1 expression in HCC cells, we focused our attention on HDAC1 and HDAC2 among the 18 different members of the family because they are often deregulated in human cancers." (PMID 28262837, 2017). "For example, stable LSD2 overexpression significantly increases the expression of LSD1, HDAC1, and HDAC2, which are important components of the NuRD (nucleosome remodeling and histone deacetylase) complex that has important implications in cancer biology." (PMID 29137219, 2017). "In TT cells, a NE cancer cell line, TDP-A dose-dependently attenuated BRET from intracellular HDAC1-NanoLuc fusion protein in low nanomolar concentrations, where the EC50 was determined to be 6.8nM." (PMID 29050323, 2017). "Numerous correlational studies reported that the HDACs expression was abnormal in human tumors, among which HDAC1, HDAC5, and HDAC7 can be used as molecular markers in early diagnosis of cancer, treatment targets and judgment of prognosis." (PMID 28624794, 2017). "In this context, previous studies have shown that HDAC1, -2, and -3 form complexes with p65 NFκB, IκBα, NuRD, N-CoR/SMRT, and other transcriptional activators and repressors important for cancer cell survival and growth." (PMID 29050320, 2017).
cancer (continued). "Eighteen HDACs were identified in mammals, among them class I HDAC family members that include HDAC1 and HDAC2, are localized in the nucleus and regulate some biological events in cancer cells, including apoptosis and proliferation." (PMID 28915616, 2017). "For instance, HDAC1 is a high impact gene in ER-negative breast cancer and a recent study showed inhibiting HDAC can sensitize cancer cells to radiotherapy." (PMID 26975659, 2016). "For example, overexpression of HDAC1, HDAC2, HDAC4, HDAC6, and HDAC7 has been observed in various cancers." (PMID 27902771, 2016). "A recent study using 115 ovarian tumour tissues confirmed that expression of nuclear HDAC1, HDAC2 and HDAC3 proteins increased stepwise in benign, borderline and malignant tumours." (PMID 26560874, 2016). "PAG1 is also reported to be controlled at epigenetic level in cancer cells, and treatment with a histone deacetylase (HDAC) inhibitor as well as by siRNA against HDAC1/2 restore PAG1 expression and activity." (PMID 26993602, 2016). "For example, HDAC1 and HDAC2 expression is often enhanced in many cancers and has been correlated with transcriptional repression of tumor suppressors, including p21." (PMID 27631103, 2016). "MDA-9/Syntenin uses its PDZ1 domain to bind with Slug, and this interaction further leads to HDAC1 recruitment, up-regulation of Slug transcriptional repressor activity, enhanced Slug-mediated EMT, and promotion of cancer invasion and metastasis." (PMID 26561205, 2016). "Although the potency of these compounds was lower compared to known HDACi TSA, apicidin and depsipeptide, they had comparable or greater selectivity of inhibition for cancer vs. normal cells and for HDAC6 vs HDAC1." (PMID 26698121, 2015). "Existing data has implied that Lsh interacts predominantly with the de novo methyltransferases Dnmt3a and Dnmt3b in MEFs, while this interaction occurs by means of HDAC1 and HDAC2 in transformed cancer cells (HCT116)." (PMID 26491684, 2015). "This protein constitutes a complex with HDAC1 (histone deacetylase-1) also via its SRA domain, which binds to methylated promoter regions of various tumor suppressor genes, including p21WAF1 in cancer cells." (PMID 26583084, 2015). "Previous studies have demonstrated that the class I and II histone deacetylases (HDACs), including HDAC1, HDAC2, HDAC3 and HDAC4, repress p21 expression in multiple human cancers." (PMID 26098774, 2015). "The percentage of HDAC1- and MTA1-positive expression in low-grade dysplasia of BM was as high as that of cancer." (PMID 25009653, 2014). "Conversely, HDAC1, CCDN1, PCNA, CDX1, KRT18, CDX2 and CASP3 are all expressed at significantly lower levels in normal tissue compared to adenomatous polyp or carcinoma tissues." (PMID 25423035, 2014). "Histone deacetylase 1 (HDAC1), a zinc-dependent deacetylase, is a member of class I histone deacetylases, it is deregulated in many cancers and plays a crucial role in cell cycle progression and proliferation." (PMID 22455563, 2012). "Having demonstrated the ability of Snail to bind and recruit histone deacetylase 1 and DNA methyltransferase 1 in this context, we set out to look for other interactions that could affect its ability to promote oncogenic transformation and cancer cell invasion." (PMID 22128911, 2011).
cancer (continued). "We also analyzed the correlation between CSNK2B expression and HDAC family‐related genes in the TIMER2.0 public database of multi‐cancer, and we found that the expression of CSNK2B showed a positive correlation with HDAC1, HADC2, HDAC5, HDAC6, and HDAC8 in LUAD and LUSC." (PMID 40013761, 2025). "Especially the class I isoforms HDAC1 and HDAC2 are overexpressed in cancer." (PMID 41409164, 2025). "Our research suggests that Paromomycin may effectively inhibit GBM by targeting HDAC1 to regulate IGF1R SUMOylation, potentially opening new avenues for GBM treatment and inspiring exploration of similar mechanisms in other cancer types." (PMID 39723246, 2024). "Thus, one of the studies focused on investigating the inhibitory effect on the epigenetic code of cancer cells, which is controlled by the UHRF1/DNMT1/HDAC1 complex." (PMID 39769174, 2024). "The overexpression of HDAC1 could be critical because it systematically regulates mitotic effectors involved in HCC progression, making it a particularly promising target for cancer therapy." (PMID 39199296, 2024). "We further validated the interaction of NOTCH1 with histone deacetylase 1 or GATAD2B using protein network analysis, proximity-based ligation, in vivo cross-linking and coimmunoprecipitation assays in several Notch-addicted cancer cell lines." (PMID 38043798, 2024). "Notably, the dual-specificity inhibitor domatinostat (4SC-202) targeting both HDAC1/HDAC2 and LSD1 catalytic activities exhibits anti-tumorigenic effects in various cancer models." (PMID 37878419, 2023). "Among them, 2-methoxyethoxy-substituted analogue 61 was found to be the most potent HDAC1 inhibitor (IC50 = 0.30 nM) with significant growth inhibition against human MDA-MB-231, H157, and A549 cancer cell lines (IC50 = 0.36–2.79 μM), even better than SAHA (IC50 = 0.36–2.79 μM)." (PMID 38139858, 2023). "Worth noting is also difluorobenzyloxy-substituted analogue 62, described as a highly potent HDAC1 inhibitor (IC50 = 0.50 nM) with promising antiproliferative properties towards the MDA-MB-231, H157, and A549 cancer cell lines with IC50 values in the range of 1.95 μM to 7.58 μM." (PMID 38139858, 2023). "For patient su008, entinostat, a benzamide histone deacetylase inhibitor targeting HDAC1 and HDAC3 treated as monotherapy or combinatorial drug together with immunotherapy to various cancers, was ranked 4th in comboSC prediction results as a drug that can be paired with immunotherapy." (PMID 38041202, 2023). "Histone deacetylase 1 (HDAC1) is a critical enzyme for epigenetic modification, whose overexpression is strongly correlated with tumor cell proliferation and growth in many cancers." (PMID 35733217, 2022). "However, small-molecule inhibitors of HDAC1, such as FK228 (romidepsin), MS-275 (entinostat) or MGCD0103 (mocetinostat), have been used to treat patients with cancer." (PMID 35104240, 2022). "Real-time quantitative PCR (qRT-PCR) analyses consistently revealed that the mRNA levels of CREPT and HDAC1 were elevated in the cancer cells when compared with the normal epithelial cells." (PMID 36230720, 2022). "The correlations between HDAC1 and the prognosis of malignant diseases are not clear since the controversial role of HDAC1 in diverse types of cancer." (PMID 35252174, 2022). "Several HDACs can act to deacetylate a certain histone in different forms of cancer: H3K9 (HDAC3), H3K14 (HDAC1, HDAC3), H3K56 (HDAC1, HDAC2), H4K5 (HDAC1, HDAC2, HDAC3), H4K8 (HDAC1, HDAC2), H4K12 (HDAC1, HDAC2, HDAC3), and H4K16 (SIRT1, SIRT2, HDAC1, HDAC2, HDAC3)." (PMID 36614156, 2022). "Interestingly, although HDAC1 and HDAC2 suppress lymphomagenesis in a dosage-dependent manner, complete inactivation of HDAC1 and HDAC2 abrogates lymphomagenesis as some level of HDAC activity is required for cancer cell vulnerability." (PMID 35887172, 2022).